RHOA (ras homolog family member A)
Diseases named in the same sentence as RHOA in open-access papers (continued):
Sharing a sentence is not in itself a finding about the gene and the disease.
psychosis (1 paper, 2025). "We investigated the role of the RhoA/ROCK1 pathway in psychosis and the potential therapeutic effect of P. cocos on psychotic behavioral changes." (PMID 40699710, 2025). "Our results revealed the role of the RhoA/ROCK1 pathway in psychosis and the potential therapeutic effect of PCEE on psychotic behavioral changes." (PMID 40699710, 2025).
pterygium (1 paper, 2019). A wedge-shaped fibrovascular lesion arising from the bulbar conjunctiva and extending to the cornea. "The accumulated amount of irradiated UV in conjunctiva may result in continuous expression of the RhoA cascade, causing the conjunctiva tissue to form pterygium via the sustained high levels of pro-inflammatory cytokines." (PMID 31547113, 2019). "Many studies have shown a strong association between the S1P–rhoA pathway and tumor progression/invasion; thus, the invasive nature of the pterygium lesion is likely to involve altered RhoA activity." (PMID 31547113, 2019). "A RhoA pull-down assay revealed that the RhoA was significantly activated in pterygium tissue and in NCFCs after UV irradiation." (PMID 31547113, 2019). "As such, we examined the activation of RhoA-ROCK signaling in pterygium tissue and after UV irradiation in NCFCs." (PMID 31547113, 2019). "In conclusion, we hypothesized that the RhoA cascade is upregulated in pterygium tissue and may play an important role in the genesis of pterygium." (PMID 31547113, 2019). "To support the hypothesis regarding the involvement of RhoA signaling in the genesis of pterygium, next, we explored MRIP, a protein that interacts directly with RhoA and its substrate (MYPT1, an endogenous inhibitor of MLCP)." (PMID 31547113, 2019). "RhoA is involved in the transdifferentiation of fibroblasts into myofibroblasts; therefore, the S1P–RhoA pathway may be involved in the pathogenesis of pterygium." (PMID 31547113, 2019). "Therefore, the present results indicate that the S1P/S1P2/RhoA pathway is upregulated in pterygium." (PMID 31547113, 2019). "Additionally, S1P upregulation induced by UV irradiation was assumed to be a factor promoting RhoA upregulation and its downstream MMP-3 or IL-8 to facilitate the onset of pterygium." (PMID 31547113, 2019). "However, the roles of S1P and the RhoA cascade in the genesis of pterygium have not been evaluated in human pterygium (until now)." (PMID 31547113, 2019). "First, the ages of the patients providing pterygium and normal conjunctiva tissues were not uniform; thus, upregulated RhoA in pterygium tissue may not only be due to accumulated UV irradiation but also may be affected by aging or other genetic confounding factors." (PMID 31547113, 2019).
Pulmonary hypoplasia (1 paper, 2015). "Pulmonary hypoplasia phenotypes, including loss of correct epithelial branching morphogenesis and cell polarity, were rescued by stimulating the non-canonical Wnt pathway downstream of the Wnt5a-TMEM67-ROR2 axis by activating RhoA." (PMID 26035863, 2015).
radiation pneumonitis (1 paper, 2023). Inflammation of the lung due to harmful effects of ionizing or non-ionizing radiation. "The results show that in radiation pneumonitis, the transcription and protein levels of MAPK and RhoA in NK cells have increased, but the changes in AKT are not significant." (PMID 38077388, 2023).
rectal tumors (1 paper, 2019). "CYT-high rectal tumors on the other hand, had recurrent deletions at loci 3p21.31 (RHOA), 5q22.2 (APC), 10q26.2 (MGMT), 14q32.2 (AKT1, EIF5, YY1), 18q21.2 (SMAD4, MAPK4), and a single amplification in 7p15.3 (STK31)." (PMID 31429779, 2019).
retinal disease (1 paper, 2021). "If the synaptic pathology is caused by RhoA activation in these disorders, ROCK inhibition could be beneficial for a broad spectrum of retinal disease." (PMID 33436892, 2021).
schistosomiasis (1 paper, 2019). An infectious disease caused by parasitic trematodes of the genus Schistosoma that colonize human blood vessels and release eggs that can cause granulomatous reactions leading to acute (swimmer's itch or acute schistosomiasis syndrome) or chronic disease. "In this study, we explored the effects of fasudil, a selective RhoA–Rho-associated kinase (ROCK) inhibitor, on Th17 cells and the pathogenesis of schistosomiasis." (PMID 31623153, 2019).
Sciatica (1 paper, 2025). Pain in the lower back and hip radiating in the distribution of the sciatic nerve. "Interestingly, ferulic acid, present in PN-G, has been earlier reported to be effective against sciatica by reducing inflammation and peripheral sensitization through targeting RhoA/p38 MAPK pathway-mediated expressions of TRPA1 and TRPV1." (PMID 40969950, 2025).
septic shock (1 paper, 2015). Shock caused by infection; frequently caused by gram negative bacteria, although some cases have been caused by other bacteria, viruses, fungi, and protozoa; characterized by fever, chills, tachycardia, tachypnea, and hypotension. "Reduced platelet aggregation in patients with septic shock was independent of molecular evidence of reduced platelet contraction, i.e. [Ser19]MLC20 phosphorylation or RhoA/ROK-dependent inhibitory phosphorylation of [Thr855]MYPT." (PMID 26215804, 2015).
signet ring cell carcinoma (1 paper, 2016). A usually aggressive, poorly differentiated invasive adenocarcinoma characterized by the presence of malignant glandular cells in which the nucleus is pressed to one side by the presence of intracytoplasmic mucus. "Signet ring cell carcinoma, a major variant of poorly cohesive carcinoma, was identified in 18 of the 22 RHOA-mutated tumors (82 %) and in 52 of the 65 RHOA wild-type tumors (80 %)." (PMID 25823974, 2016).
skin infection (1 paper, 2021). An inflammatory process affecting the skin, caused by bacteria, viruses, parasites, or fungi. "Furthermore, T cell migration in non-lymphoid tissues is dependent on RhoA and the absence of RhoA in these cells results in impaired control of skin infections." (PMID 34422807, 2021).
steatosis (1 paper, 2023). Increased lipid within the cytoplasm of cells. "Simvastatin, another mevalonate pathway suppressor, has been shown to prevent fibrosis and inflammation in NAFLD by suppressing RhoA- and Ras-mediated pathways without affecting steatosis." (PMID 36839192, 2023).
thrombotic microangiopathy (1 paper, 2016). The syndromes of microangiopathic hemolytic anemia, thrombocytopenia, and variable signs of organ impairment, due to platelet aggregation in the microcirculation. "In addition, RhoA alterations could be associated with lymphovascular invasion, causing carcinomatous lymphangiosis or pulmonary tumor thrombotic microangiopathy in some extreme cases because RhoA is important in the transendothelial migration of neoplastic cells." (PMID 25823974, 2016).
thymic lymphoma (1 paper, 2025). "A prior study demonstrated that inhibition of RHOA function in the thymus resulted in aggressive thymic lymphoma of T–cell origin, suggesting that RHOA–mediated signalling is crucial for T–cell transformation." (PMID 41362935, 2025).
urothelial carcinoma (1 paper, 2025). A malignant neoplasm derived from the transitional epithelium of the urinary tract (urinary bladder, ureter, urethra, or renal pelvis). "In the PPI network specific to nonpapillary urothelial carcinoma, network B, we identified GNB1, RHOA, UBC, and FPR2 as hub proteins, which were involved in the PI3K/AKT signaling pathway." (PMID 41342186, 2025).
uveitis (1 paper, 2024). An inflammatory process affecting a part of or the entire uvea. "Interestingly, a peptide inhibiting RHOA activation by GEF-H1 has been shown to inhibit blood vessel leakage in a mouse model of uveitis, opening the door to a new therapeutic approach." (PMID 38312316, 2024).
vascular dementia (1 paper, 2023). A degenerative vascular disorder affecting the brain. "Ras homolog gene family member A (RhoA) involved in vascular dementia and serves as potential targets of new drugs for vascular dementia treatment." (PMID 37388929, 2023).
xeroderma pigmentosum (1 paper, 2020). Xeroderma pigmentosum (XP) is a rare genodermatosis characterized by extreme sensitivity to ultraviolet (UV)-induced changes in the skin and eyes, and multiple skin cancers. "Therefore, skin-derived cells from Xeroderma Pigmentosum patients were used to investigate the interplay between RhoA and NER proteins." (PMID 33015036, 2020).
Yersinia infection (1 paper, 2021). "While prior to Yersinia infection, wild-type OTUB1 catalyzes the deubiquitination of active-form RhoA to stabilize the protein, and then enhances the cellular susceptibility to invasion." (PMID 34277632, 2021).
Yersinia pseudotuberculosis infection (1 paper, 2012). "Other publications however indicate that upon Yersinia pseudotuberculosis infection YopT cleaves RhoA as well as Rac and Cdc42 from nascent phagosomes and affects RhoG." (PMID 22792400, 2012).
tumor (713 papers, 1998 to 2026). "Mechanistic studies revealed that tumor-derived ANG binds epidermal growth factor receptor (EGFR) on tumor-associated macrophages (TAMs), activating RhoA-dependent cytoskeletal remodeling and autocrine ALK5/TGFβ signaling." (PMID 41975075, 2026). "We demonstrated that the molecular mechanisms underlying M2 polarization involve PI3K, AKT, and RhoA activation, suggesting a pathway by which tumor cells induce M2 macrophage infiltration." (PMID 39953613, 2025). "In conclusion, our study establishes RHOA lactylation as a metabolic analog of oncogenic mutations, where lactylations at K118 (activation) and K162 (stabilization) drive tumor progression through constitutive RHOA signaling." (PMID 41291745, 2025). "The Ras homolog family member A (RhoA)/Rho-associated protein kinases (ROCKs) signaling pathway plays a critical role in regulating cellular migration, invasion, and tumor progression in BC." (PMID 40388100, 2025). "The p27 protein can inhibit the transduction of the rho-associated kinase (RhoA) signaling pathway, consequently reducing the migratory and invasive capacity of tumor cells." (PMID 40140925, 2025). "Multiple studies have demonstrated concordance between the detection of RHOA G17V mutations in both ctDNA and tumour AITL samples." (PMID 40724970, 2025). "In this process, reduced FAK/RhoA signaling, a downstream effector of EphA2, was associated with attenuated tumor progression in RCC." (PMID 41440001, 2025). "While Piezo1 promotes processes such as epithelial remodeling and tumor invasion via pathways like RhoA/ROCK and YAP/TAZ, Piezo2 is more associated with sensory neuron activity, immune modulation, and tumor aggressiveness." (PMID 42211053, 2025). "The compilation of RHOA crystal structures showed that WT-RHOA, RHOA lactylation-mimicking variant (K118Q) and tumor-associated mutant variants (K118N and K118R) had extremely similar conformations in GTP and its binding region." (PMID 41291745, 2025). "Our results revealed that a subset of patients with a high VAF ratio of TET2 to RHOA mutations, possibly indicating the expansion of non-tumor cells carrying TET2-CH, had a significantly worse prognosis than the low-ratio group." (PMID 40164718, 2025). "Recent studies have proposed that driver mutations, such as EGFR mutations or RHOA mutations, are associated with the immunosuppressive tumor microenvironment." (PMID 38455493, 2024). "During the mature T cell phase, the emergence of tumor-specific mutations like RHOA (G17V) and IDH2 (R172) play a role in the progression of AITL." (PMID 39229263, 2024). "So far, only a few target genes associated with eIF5A hypusination have been reported in tumor cells, such RhoA and MYC." (PMID 38654332, 2024). "For example, recent publications have identified mTOR signaling and the SEMA6A/RHOA/YAP axis as off-target mechanisms in BRAFi-associated tumor-protective effects of fibroblasts in the TME." (PMID 38839106, 2024). "RHOA has been implicated in T cell activation and migration, which are critical for effective anti-tumor immune responses." (PMID 39050251, 2024). "Mechanistically, integrin β8 was identified to transduce mechano-signaling to trigger tumor cell dedifferentiation by recruiting RhoGDI1 to inactivate RhoA and subsequently Yes-associated protein (YAP)." (PMID 37614365, 2023). "Among various types of cancer especially ESCC, the activity of Rho GTPase, in particular those of the family (including most studied members RhoA, Rac1, and Cdc42), have been strongly associated with tumor progression." (PMID 37752569, 2023). "The RhoA/Rho pathway is one of the important pathways implicated in tumor cell migration and invasion." (PMID 37446748, 2023). "This is relevant because, according to the Gene Cards Human Gene Database, overexpression of RHOA is associated with tumor cell proliferation and metastasis, while THBS1 plays a role in platelet aggregation, angiogenesis, and tumorigenesis." (PMID 35628184, 2022).
tumor (continued). "Univariate analysis suggested that the expression levels of ARHGAP25 and RhoA, VM, tumor size, TNM stage, and LNM were strongly linked with OS and DFS, which are critical factors influencing the future prognosis with NSCLC." (PMID 36207695, 2022). "In this experiment, the tumor environment only caused increases in RhoA, ROCK1 and ROCK2, and other components of this signaling pathway were not elevated." (PMID 35811723, 2022). "Dysregulation of activity of both Rac1 and RhoA has been linked to mesenchymal tumor movement and invasive phenotypes in cancer." (PMID 35241781, 2022). "Previous studies have shown that abnormal expression of RhoA is common in a variety of tumors, including CRC, and activation of RhoA was associated with tumor metastasis." (PMID 35619906, 2022). "Heterogeneous nuclear ribonucleoprotein C1/C2 (HNRNPC) and RhoA have been implicated in the regulation of tumour cell proliferation and chemo‐ and radioresistance." (PMID 35277915, 2022). "Pathogenic or likely pathogenic mutations detected in the original patient tumors were also detected in the PDX tumors, with one exception: a mutation in RHOA was only found in the primary patient tumor of HROC419." (PMID 34884989, 2021). "RhoA knockdown was associated with significantly reduced tumor growth and increased sensitivity to MPPa-PDT, while RhoA overexpression had the opposite effect." (PMID 34627383, 2021). "Diffuse Lauren type, poorly differentiated tumors, moderate/intense inflammatory infiltrate, depth of tumor invasion, and advanced pTNM stage were associated with the low-RhoA group." (PMID 35076580, 2021). "ARF1 and RhoA have been implicated in some aspects of cancer development, including tumor cell invasion and proliferation (40, –, 45)." (PMID 34903051, 2021). "The mutational profile of the CTNNA1 germline mutated tumour encompassed somatic mutations in RHOA, a specific DGC and PCC‐NOS gene, and in ARID1A and PIK3CA, genes transversally mutated in both DGC and IGC." (PMID 33724653, 2021). "Further evidence revealed by Xi Huang and his colleagues linked RhoA activation to the arrest of circulating tumor cells in vivo." (PMID 33302361, 2020). "Together with the effects on the size of the tumor nests, our results suggest that RHOA mutations are likely to have a direct role in the development of the morphology that is distinctive of clinical DGC." (PMID 31485674, 2019). "These cells have the intrinsic ability to secrete SPARC when exposed to mechanical stress, such as that caused by RhoA-induced actomyosin constriction, which enables them to migrate away from the cell-dense and nutrition-deprived bulk of the tumor." (PMID 31062076, 2019). "We carried out preliminary genetic characterisation by whole exome sequencing and detected tumor specific mutations in Hsp90ab1, Ccnb3 and RhoA." (PMID 31013298, 2019). "It has been reported that TPM2 was found to be downregulated in CRC, and TPM2 loss was related with RhoA activation and tumor proliferation in CRC." (PMID 30446877, 2019). "As shown in our model, we have identified an original role of Ran in association with the PM to control tumor cell invasion by functionally and specifically linking it to RhoA signaling." (PMID 31209254, 2019). "TPM2 loss is associated with Ras homolog gene family member A (RhoA) activation and tumor proliferation and transfer." (PMID 31487691, 2019). "This information prompted us to study the effects of RHOA mutations in vivo by inoculating the tumor cells into the stomachs of SCID mice." (PMID 31485674, 2019). "RHOA is involved in signal transduction, actin cytoskeleton dynamics, and its overexpression is associated with tumor growth." (PMID 30392061, 2019). "Another notable morphological finding in the present study was that, in contrast to mock and WT tumors, RHOA-mutated tumors had little host reaction in the invasive front of the tumor." (PMID 31485674, 2019).